NAP1L3 (nucleosome assembly protein 1 like 3)
Description:
Histone chaperone (By similarity). May play a role in cellular differentiation.
Synonyms: MB20; NPL3; MGC26312
Tractability: PROTAC: ubiquitination databases record sites on it.
Gene: Protein-coding gene on chromosome X (93,670,930 to 93,673,578, reverse strand). Ensembl gene ENSG00000186310.
Subcellular location: Nucleus
Subcellular location (Human Protein Atlas): Vesicles; Nucleoli; Nucleoplasm
Gene Ontology:
Molecular function: protein binding
Biological process: nucleosome assembly
Cellular component: nucleus; chromatin
Homologues: Orthologues: chimpanzee NAP1L3 (99% identical), macaque NAP1L3 (97% identical), rabbit NAP1L3 (81% identical), pig NAP1L3 (78% identical), mouse Nap1l3 (78% identical), rat Nap1l3 (76% identical), zebrafish nap1l4a (26% identical), Drosophila melanogaster Nap1 (22% identical), Drosophila melanogaster CG3708 (20% identical), Caenorhabditis elegans nap-1 (18% identical), Drosophila melanogaster mil (17% identical), zebrafish tspy (13% identical), and 2 more. Paralogues in human: NAP1L1 (32% identical), NAP1L2 (32% identical), NAP1L4 (26% identical), TSPYL4 (13% identical), SETSIP (12% identical), TSPYL1 (12% identical), TSPYL2 (12% identical), SET (12% identical), TSPYL6 (11% identical), TSPYL5 (11% identical), TSPY1 (10% identical), TSPY10 (10% identical), and 6 more.
Diseases named in the same sentence as NAP1L3 in open-access papers:
NAP1L3 is named in the same sentence as 9 diseases in open-access papers, as found by Europe PMC text mining. Sharing a sentence is not in itself a finding about the gene and the disease. The quoted sentences say what the papers report.
hepatocellular carcinoma (2 papers, 2021 to 2024). A malignant tumor that arises from hepatocytes. "Additionally, the oncogenes, ALDH5A1 and NAP1L3, exerted effects in papillary thyroid carcinoma and hepatocellular carcinoma, respectively." (PMID 38552216, 2024).
leukaemia (1 paper, 2018). "Although the transplanted animals in this study did not display any features of malignant transformation into leukaemia, this overexpression in AML cells together with a strong association to HOXA genes, cell cycle progression, MYC and E2F, indicate that NAP1L3 may have a role in leukemogenesis." (PMID 30046127, 2018).
myeloma (1 paper, 2015). "Notably, six of the top deregulated genes (NUDT11, PKP2, ROBO1, AGAP1, NAP1L3 and EPDR1) were recently identified as “stem cell” genes in myeloma." (PMID 24913504, 2015). "It is also noteworthy that the 37 top deregulated genes were enriched for the myeloma “stem cell” gene set, including NUDT11, PKP2, ROBO1, AGAP1, NAP1L3 and EPDR1, indicating that “stemness” may play an important role in determining high risk behavior." (PMID 24913504, 2015).
tumor (2 papers, 2021 to 2023). "We found that circGFRA1 over-expression markedly elevated the tumor growth rate and tumor volume, accompanied by the up-regulation of NAP1L3." (PMID 33431945, 2021). "Interestingly, studies in other cancers had already identified WTIP, NAP1L3, and CCDC91, as relevant genes for tumor progression." (PMID 37772256, 2023).
NAP1L3 also shares sentences with these, for which no sentence is quoted: breast carcinoma (1 paper); cancer (1); Intellectual disability (1); pancreatic neuroendocrine neoplasm (1); papillary thyroid carcinoma (1).